RBBP6 (RB binding protein 6, ubiquitin ligase)
Diseases named in the same sentence as RBBP6 in open-access papers (continued):
Sharing a sentence is not in itself a finding about the gene and the disease.
oesophageal cancer (2 papers, 2006 to 2023). "Cell cycle arrest, a characteristic of carcinogenesis that is caused by RBBP6 overexpression, is significantly linked to the growth of cervical and oesophageal cancer tumors." (PMID 36853473, 2023). "RBBP6 has recently been shown to be highly up-regulated in oesophageal cancer, and to be a promising target for immunotherapy against the disease." (PMID 16396680, 2006). "Cytotoxic T cells specific for RBBP6-derived peptides were able to lyse oesophageal cancer cells in culture, and to produce regression of oesophageal tumours in mice xenograft models." (PMID 16396680, 2006). "Recently it has been reported that RBBP6 is strongly up-regulated in oesophageal cancer cells, and high levels of expression correlate with higher rates of proliferation in cultured oesophageal cancer cell and low survival rates in cancer patients." (PMID 16396680, 2006).
Autoimmunity (1 paper, 2024). The occurrence of an immune reaction against the organism's own cells or tissues. "RBBP6 might prevent premature T cell death during the active response phase and ensure appropriate apoptosis afterward to avoid autoimmunity or chronic inflammation." (PMID 39066192, 2024).
cervical tumours (1 paper, 2019). "RBBP6 upregulation was directly proportional to the high apoptosis levels in cervical tumours." (PMID 30886526, 2019).
cholangiocarcinoma (1 paper, 2025). A carcinoma that arises from the intrahepatic biliary tree (intrahepatic cholangiocarcinoma) or from the junction, or adjacent to the junction, of the right and left hepatic ducts (hilar cholangiocarcinoma). "Additional evidence from the GEPIA database revealed an unusual increase in RBBP6 levels in cholangiocarcinoma tissues, along with reduced IκBα levels." (PMID 39836545, 2025).
colorectal tumor (1 paper, 2019). "We found that the DNA methylation on the promoter of RBBP6 was similar in colorectal tumor and normal colon tissue, but the DNA methylation on the first intron of RBBP6 was higher in CRC comparing to normal colon tissue." (PMID 31685801, 2019).
diabetic kidney disease (1 paper, 2024). Progressive kidney disorder caused by vascular damage to the glomerular capillaries, in patients with diabetes mellitus. "explore the role of estrogen‐related receptor α (ERRα) in diabetic kidney disease (DKD), revealing retinoblastoma binding protein 6 (RBBP6) as a key regulator of ERRα degradation." (PMID 39441040, 2024).
dysplasia (1 paper, 2019). A usually neoplastic transformation of the cell, associated with altered architectural tissue patterns. "There were significantly elevated levels of RBBP6 protein at all grades of invasive carcinoma and those of dysplasia." (PMID 30886526, 2019).
glioblastoma (1 paper, 2024). The most malignant astrocytic tumor (WHO grade IV). "Our identification of the dependency on the RBBP6/CPSF3-APA-MYC axis in glioblastoma offers novel strategies for lethal cancers." (PMID 38503731, 2024). "Of the 6 shared genes, only the mRNA expression of RBBP6 was upregulated in glioblastoma tissue compared to normal brain tissue." (PMID 38503731, 2024). "In summary, by utilizing an in vitro and in vivo CRISPR screening, we identified the dependency on the RBBP6/CPSF3-APA-MYC axis in glioblastoma." (PMID 38503731, 2024). "Our data suggest that approaches to modulate APA in GSCs by targeting RBBP6 or CPSF3 showed high therapeutic efficacy, offering novel strategies for glioblastoma treatment." (PMID 38503731, 2024). "Collectively, these results demonstrated that RBBP6 and CPSF3 are potential therapeutic targets in glioblastoma." (PMID 38503731, 2024). "Collectively, RBBP6 maintains high MYC expression in GSCs through regulation of CPSF3-dependent alternative polyadenylation, providing a potential therapeutic paradigm for glioblastoma." (PMID 38503731, 2024).
glioma (1 paper, 2024). A benign or malignant brain and spinal cord tumor that arises from glial cells (astrocytes, oligodendrocytes, ependymal cells). "Analysis of TCGA and Chinese Glioma Genome Atlas (CGGA) datasets revealed that RBBP6 mRNA levels were positively correlated with MYC mRNA levels." (PMID 38503731, 2024). "We then performed in silico analysis to confirm that high RBBP6 and CPSF3 expression correlated with worse survival in glioma patients." (PMID 38503731, 2024).
intrahepatic cholangiocarcinoma (1 paper, 2025). A carcinoma that arises from the intrahepatic bile duct epithelium in any site of the intrahepatic biliary tree. "In intrahepatic cholangiocarcinoma (ICC) models, the translation product of circPCSK6, circPCSK6-167aa, competitively binds to the RING domain of the E3 ubiquitin ligase RBBP6, inhibiting K48 ubiquitination of IKBα and preventing its degradation." (PMID 40872908, 2025).
lymph node metastasis (1 paper, 2013). "Of the 66 samples of available lymph node metastasis (LNM) specimens, 58 samples (87.9%) showed RBBP6 overexpression." (PMID 23799110, 2013).
metastatic tumors (1 paper, 2019). "As the result showed, RBBP6 overexpression not only dramatically increased the number of lung metastatic tumors, but also remarkably increased the average diameter of the metastatic tumors." (PMID 31685801, 2019).
myeloproliferative neoplasm (1 paper, 2015). A clonal hematopoietic stem cell disorder, characterized by proliferation in the bone marrow of one or more of the myeloid (i.e., granulocytic, erythroid, megakaryocytic, and mast cell) lineages.
Obesity (1 paper, 2018). Accumulation of substantial excess body fat. "We observed a nominally significant association for only two T2D markers in RREB1 and PRKAG1, one obesity (OB) marker in the OR2Y1 gene, and for several BMI markers in the ACP1, RBBP6, and C14orf39 genes." (PMID 30126146, 2018).
prostate carcinoma (1 paper, 2023). A carcinoma that arises from epithelial cells of the prostate gland. "We demonstrated that cannabidiol is a viable therapy to treat prostate cancer cells, in combination with silencing of RBBP6." (PMID 36853473, 2023). "Therefore, we performed the MTT assay to evaluate the effect of Cannabis sativa extract and CBD on prostate cancer cell proliferation in combination with RBBP6 silencing." (PMID 36853473, 2023).
squamous carcinoma (1 paper, 2019). "Immunohistochemistry showed that the RBBP6 proteins were highly expressed in moderately differentiated squamous carcinoma." (PMID 30886526, 2019). "However, in well-differentiated squamous cell carcinoma, apoptosis levels were low and these are the same tissues where RBBP6 was upregulated." (PMID 30886526, 2019).
Thrombocytosis (1 paper, 2025). Increased numbers of platelets in the peripheral blood. "For example, RBBP6 pathogenic variants increase the risk of myo-proliferative neoplasms, which can involve hemorrhaging, thrombocytosis, and coagulopathy, similar to severe YF." (PMID 40631121, 2025).
viral disease (1 paper, 2025). "This link between RBBP6 and hereditary and viral disease is reminiscent of previous findings connecting hereditary and ZIKV-induced microcephaly." (PMID 40631121, 2025).
cancer (22 papers, 2006 to 2026). A tumor composed of atypical neoplastic, often pleomorphic cells that invade other tissues. "The expression of RBBP6 in malignancies is also associated with the sensitivity of cancer cells to certain chemotherapeutic agents and radiotherapy." (PMID 38667315, 2024). "Rbbp6 is a RING finger-domain E3 ubiquitin ligase which is upregulated in various cancers and associated with poor prognosis." (PMID 39580381, 2024). "Hallmark enrichment analysis revealed that RBBP6 knockdown downregulated several signaling pathways essential for cancer progression, including MYC, TNFA-NFKB, and estrogen response signaling pathways." (PMID 38503731, 2024). "In an attempt to differentiate between the two bigger transcripts, an exon 16 probe was used and there was high stromal expression of RBBP6 variant 1 compared with well-differentiated carcinoma." (PMID 30886526, 2019). "Moderately differentiated carcinoma showed elevated levels of RBBP6 variants 1 and 2 compared with that observed in well-differentiated carcinoma." (PMID 30886526, 2019). "From tissue sections, we further showed that RBBP6 expression is associated with advancement of cancer." (PMID 30237738, 2018). "In this study, RBBP6 expression was associated with ‘T’ category cancer with regards to invasion depth, distant metastasis, lymph node metastasis, and clinical stage." (PMID 25379943, 2014). "We found that RBBP6 expression was significantly associated with advanced cancer biology, which was indicated by invasion depth, LNM, and distant metastasis." (PMID 23799110, 2013). "Despite its potential as an anti-cancer target and its apparently close association with transcription and the cell cycle, very little is known about the function of RBBP6." (PMID 16396680, 2006). "In addition, RBBP6 was also reported as a cancer-related protein that has been implicated in the regulation of the cell cycle and apoptosis through the JNK signaling pathway." (PMID 38200098, 2024). "The RBBP6 gene, which has different variants, has been reported to be involved in cancer development but it remains unclear which RBBP6 product is involved in cancer development." (PMID 31534777, 2019). "Taken together, these findings indicate that RBBP6 may be an important target for anti-cancer drugs, as well as a candidate diagnostic marker." (PMID 25955646, 2015). "RBBP6 is emerging as an attractive candidate for the development of anti-cancer drugs due to its role in cell proliferation and altered expression patterns associated with certain cancers." (PMID 25955646, 2015). "Different RBBP6 variants could be targeted for cancer therapeutic development." (PMID 31534777, 2019). "We also evaluated the prognostic and predictive significance of RBBP6 as a potential cancer biomarker and its suitability as a molecular target in cancer." (PMID 42239902, 2026). "This is the first review that comprehensively explores the multifaceted molecular mechanisms by which RBBP6 influences cancer progression in several cancer types." (PMID 42239902, 2026). "This review captures the molecular functions of RBBP6 and the mechanisms by which aberrant RBBP6 expression and function influence cancer development and therapeutic response." (PMID 42239902, 2026). "This suggests that combined targeting of Mdm2 and RBBP6 would produce a good treatment for cancers that overexpress these molecules." (PMID 39857778, 2025). "Assessing the role of RBBP6 in CC cell response to cisplatin in vivo using a cancer mouse model will potentially shed more light on the molecular mechanisms of cisplatin-acquired resistance." (PMID 38667315, 2024).
cancer (continued). "The RBBP6 gene is alternatively spliced to generate three protein isoforms that are differentially expressed in different tumor stages, with more advanced cancers exhibiting higher levels of RBBP6 compared to less advanced stages." (PMID 38667315, 2024). "As shown in previous studies, RBBP6 is highly expressed in cancer cells and plays a major role in cell proliferation." (PMID 36853473, 2023). "In conjunction with RBBP6 expression, arsenic trioxide, cobalt chloride and curcumin should be further explored as cancer drugs." (PMID 31534777, 2019). "Poorly and moderately differentiated carcinoma showed high expression levels of RBBP6 proteins both in the cytoplasm and in the nucleus." (PMID 30886526, 2019). "In contrast, a well-differentiated carcinoma showed low levels of RBBP6 protein expression both in the cytoplasm and in the nucleus." (PMID 30886526, 2019). "The RBBP6 proteins were highly expressed in the cytoplasm and some nuclei of moderately differentiated and well-differentiated carcinomas." (PMID 30886526, 2019). "At the gene level, it was clear from the band intensity observed in gel electrophoresis that the more advanced the cancer is, the higher the expression of RBBP6; however, at the earlier stages of the cancer, the expression is less." (PMID 30237738, 2018). "The fact that RBBP6 was found to be expressed differentially in several tissues suggests a pivotal role it plays in cancer progression and as a potential biomarker for targeted cancer therapy." (PMID 30237738, 2018). "RBBP6 was observed to be concentrated or overexpressed in the cytoplasm and partially in the nuclei in moderate cancers." (PMID 30237738, 2018). "The expression of RBBP6 was also stronger in advanced cancer tissues than in moderate one, suggesting that the more the cells divide the more they express RBBP6." (PMID 30237738, 2018). "We found that two isoforms of RBBP6 are inducible by these drug treatments in cancer and normal cells." (PMID 28797070, 2017). "Moreover, RBBP6 is reported to be a prognostic marker and an inducer of cancers such as colorectal and non-small lung cancer." (PMID 39857778, 2025). "Also, more information is emerging regarding the role of RBBP6 in cancer treatment; specifically, its potential to sensitize cancer cells to radiation and chemotherapeutic agents, such as camptothecin, staurosporine, and GABA." (PMID 38667315, 2024). "When coupled with RBBP6 silencing, cisplatin may considerably reduce the development of cancer cells compared to therapy with either drug alone." (PMID 36853473, 2023). "In various human cancers, RBBP6 is involved in the regulation of cell cycle and apoptosis." (PMID 36915078, 2023). "This, therefore, suggests that RBBP6 may serve a critical role in the malignant phenotype of human cancer." (PMID 36853473, 2023). "Furthermore, RBBP6 is a critical element in carcinogenesis and has been identified as a potential biomarker for certain cancers." (PMID 36763571, 2023). "RBBP6 is overexpressed in several cancers and has been identified as a potential cancer biomarker." (PMID 36763571, 2023).
cancer (continued). "Treatment of a variety of cancer cells with DNA methyltransferase inhibitors (DNMTi) results in downregulation of ZBTB38 protein expression via proteasomal degradation due to upregulation RBBP6." (PMID 35178492, 2022). "Interestingly, RBBP6 was also highly expressed in highly invasive cancer cells (SW620, Caco2, HT29, LoVo) compared with low-invasive cancer cells (RKO, SW480, HCT15)." (PMID 31685801, 2019). "However, more study is needed to clarify the mechanism by which RBBP6 increases in a variety of cancers." (PMID 31685801, 2019). "This suggests that RBBP6 may serve a critical role in the malignant phenotype of human cancer." (PMID 38667315, 2024). "In addition to this, the results indicated that RBBP6 may promote tumorigenesis by increasing cancer cell proliferation." (PMID 36853473, 2023). "We then directly investigated the relationship between RBBP6, USP9X, ZBTB38, and CDKN1C expression and the clinical response to azacytidine in cancer patients." (PMID 30310057, 2018). "On the other hand, hypomethylation of oncogenes, such as retinoblastoma binding protein 6 (RBBP6), solute carrier family 34 member 2 (SLC34A2), and lymphocyte antigen 6 complex locus K (LY6K), is frequently observed in numerous cancers, facilitating aberrant gene activation." (PMID 40663150, 2025).